CSF1R (colony stimulating factor 1 receptor)
Diseases named in the same sentence as CSF1R in open-access papers (continued):
Sharing a sentence is not in itself a finding about the gene and the disease.
tumor (continued). "Reprogramming myeloid cells to a more tumor supportive phenotype has gained attention by targeting the colony-stimulating factor 1 receptor (CSF1R)." (PMID 36011015, 2022). "The combination of oncolytic virus, CSF-1R inhibition and anti-PD-1 immunotherapy was found to enhances anti-tumor immune response by increasing T cell infiltration and augmenting anti-tumor CD8+ T cell function." (PMID 35874717, 2022). "This CSF1R/PD-L1 axis in Lal–/– CD11c+ MDSCs was, at least in part, responsible for their ability to suppress T cells and stimulate tumor growth." (PMID 35917184, 2022). "Regorafenib targets multiple receptor tyrosine kinases, including those involved in tumor angiogenesis (VEGFR-1, -2, -3, endothelial-specific receptor tyrosine kinase 2 (TIE2)) and tumor immunity (Colony stimulating factor 1 receptor (CSF1R))." (PMID 36142591, 2022). "Cytokine negatively regulates IFNγ signaling through CSF1R expression, thus modulating the functions of tumor infiltration." (PMID 35433686, 2022). "The role of the CSF-1R/CSF-1 axis has been studied in many cancer types, because tumor cells secrete CSF-1 to attract CSF-1R+ myeloid-derived cells to the tumor microenvironment to sustain tumor progression." (PMID 35115369, 2022). "Several factors are involved in the attraction of TAMs to the tumor site, including CSF-1 receptor (CSF-1R) and granulocyte-macrophage colony-stimulating factor (GM-CSF)." (PMID 35203505, 2022). "Pharmacologic targeting of this axis mainly relies on anti-CSF1 or anti-CSF1R agents as well as on CSF1R tyrosine kinase inhibitors (TKIs) and has shown anti-tumor activity in several pre-clinical models." (PMID 36077813, 2022). "Monocytes and macrophages from the bone marrow and spleen can respond to tumor-derived factors, such as CSF-1, and initiation of the CSF-1R signaling cascade results in their proliferation, differentiation, and migration to the tumor." (PMID 35821822, 2022). "Immune and stromal cell populations included 2 populations: Macrophages 1 (c1: C1qa, C1qb, C3aR1, Cd68, Csf1r, Tlr2, and Cd86) and 2 (c6 + c9: Ccr7, Csf2rb, Il1b, and Cd74) expanded in PNs as a percentage of total tumor cells." (PMID 36134665, 2022). "CSF1R inhibitors have been shown to repolarize TAMs toward an antitumor phenotype, enhance the efficacy of immunotherapies, and retard tumor progression, and they have a low-toxicity profile." (PMID 35315360, 2022). "IL-34 function is mainly mediated by interaction with the macrophage colony-stimulating factor-1 receptor (MCSF-1R), which is also over-expressed by CRC cells as well as by tumour-associated macrophages (TAMs) and cancer-associated fibroblasts." (PMID 35837402, 2022). "Using 4NQO-LCSF-1 and 4NQO-LGFP tumors we provided further evidence to support the influence of tumor-derived CSF-1 on CSF-1R+CD11c+ MDSCs and CD8+ T cells in response to therapy in vivo." (PMID 35292516, 2022). "Meanwhile, the colony-stimulating factor-1 receptor (CSF-1R) signaling pathway can contribute to the immunosuppressive tumor microenvironment, and its inhibitors are currently being investigated in clinical trials." (PMID 36213111, 2022). "CSF-1R inhibitors are available to block macrophage CSF-1R and reduce the number of M2-type macrophages, ultimately increasing the response of tumor cells to PD-1 antibodies." (PMID 36612100, 2022). "It has been found that OS tumor cell-intrinsic CSF1R can enhances cell proliferation and metastasis by CSF-1R/JAG1 axis or ERK signaling pathway." (PMID 35078433, 2022). "The 3D185 is a new type of effective inhibitor blocking CSF-1R, which leads to reprogramming of TAMs and delays tumor growth in preclinical evaluation." (PMID 35672862, 2022). "In tumor-bearing mice, Ly6Chigh monocytes increased with tumor growth in the spleen in the elderly and increased intracellular CSF-1R expression occurred in bone marrow Ly6Chigh monocytes in elderly mice bearing large tumors." (PMID 35821822, 2022).
tumor (continued). "The increase in CD11b+CD45lo microglia was observed with enhanced cell surface expression of CD115 (the colony stimulating factor 1 receptor, CSF1R) on microglia from the brains of secondary tumor-bearing MMTV-Wnt1 mice." (PMID 35382852, 2022). "In line with the results obtained after the chronic treatment, fluorescent labeling revealed the presence of TSPO+ and CSF-1R+ immune cells infiltrating the tumor after depletion of microglia cells." (PMID 35115369, 2022). "Our findings provide genetic proof of an important role of Csf1r down-regulation for tumor suppression by Mir34a during intestinal tumorigenesis." (PMID 36147476, 2022). "The inhibition of CXCR2 alone resulted in enhanced T cell infiltration, and when combined with checkpoint blockade or CSF-1R inhibition, tumor responses were enhanced." (PMID 35205732, 2022). "Combined with the overall changes to CSF-1R expression it is possible there is increased utilization of CSF-1 in elderly tumor-bearing mice." (PMID 35821822, 2022). "The anti-tumor effect of CSF-1R inhibition, which leads to inhibition of macrophage recruitment in cancer tissue, showed limited anti-tumor activity as a monotherapy." (PMID 36470862, 2022). "For this, the biotin-switch assay was performed to measure S-Nitrosylated (S-NO) CSF1R proteins from tumor grafts from mice exposed to GSNO treatment." (PMID 36209194, 2022). "CSF-1R is expressed in myeloid cells such as macrophages, dendritic cells (DCs), neutrophils, and myeloid-derived suppressors (MDSCs) within the tumor microenvironment (TME)." (PMID 36555334, 2022). "Here, we determined a tumor suppressive role for Mir34a, whereas Csf1r displayed a tumor-promoting function in intestinal epithelial cells." (PMID 36147476, 2022). "To that end, we injected wild-type and GNE-KO MC38 tumor cells into C57BL/6 mice while depleting either Ly6G+ granulocytes or colony-stimulating factor 1 receptor 1–positive (CSF1R+) TAMs." (PMID 36322632, 2022). "We showed that CSF1R+ macrophages promoted pleural fluid accumulation by enhancing vascular permeability, destabilizing tumor vessels, and favoring immune suppression." (PMID 35315360, 2022). "Depletion of CSF-1/CSF-1R was shown to significantly inhibit tumour progression and metastasis in various tumour models." (PMID 36131942, 2022). "Tumour infiltrating monocytes are predominantly Ly6Chigh and can be recruited via CSF-1/CSF-1R signaling." (PMID 35821822, 2022). "To confirm these findings in vivo, we depleted TAMs by treating BP tumor-bearing mice with an anti-CSF1R antibody." (PMID 35641483, 2022). "CSF1R controls Lal–/– CD11c+ cells’ PD-L1 regulation, T cell suppression, and tumor growth stimulation." (PMID 35917184, 2022). "Inhibition of CSF-1/CSF-1R signaling reduced the tumor-infiltrating MDSCs and enhanced the anti-tumor T cell responses." (PMID 35585567, 2022). "The results of gene enrichment analysis showed that CSF-1R was involved in tumor immune response and regulation of TME." (PMID 35444953, 2022). "Overall levels of F4/80 staining within tumours was significantly higher in mice treated with M279 (CSF-1R mAb) compared to TKP treatment mice (p < 0.05)." (PMID 35359423, 2022). "Here the authors design an alginate-based hydrogel encapsulating anti-PD-1-conjugated platelets and nanoparticles loaded with the macrophage-depleting CSF-1R inhibitor pexidartinib, showing inhibition of post-surgery tumor recurrence in preclinical models." (PMID 35387972, 2022). "In a mouse proneural GBM model, CSF-1R blockade significantly inhibited GBM tumor growth and prolonged survival." (PMID 35967394, 2022). "Previous studies conducted in mouse model and in patients demonstrated that antibody blockade of CSF-1R dramatically decreased the number of TAMs in tumor tissues." (PMID 36359228, 2022). "Subsequently, combination of CSF-1R inhibition with androgen blockade therapy or irradiation reduced tumor progression in subcutaneous PC mouse models." (PMID 35053602, 2022).
tumor (continued). "Researchers have shown that CSF-1R inhibitor-loaded nanoparticles efficiently deplete TAMs and inhibit tumor growth and metastasis." (PMID 35183252, 2022). "A biodegradable dextran nanoparticle is formulated to encapsulate and bioresponsively release PLX to block CSF1R to eliminate TAMs in the tumor microenvironment." (PMID 35387972, 2022). "It is produced by many tumors, and its elevated serum levels or the high expression of its receptor CSF-1R on the tumor cells correlate with tumor grade and poor prognosis in cancer patients." (PMID 36561751, 2022). "During neoplasm development in the mammary gland, the application of colony‐stimulating factor 1 receptor (CSF1‐R) inhibitors can deplete TAMs to effectively inhibit metastasis, angiogenesis and reduce the invasiveness of the tumor." (PMID 34914196, 2022). "To this end, we treated 4NQO-L tumor-bearing mice with the CSF1R inhibitor PLX3397 (pexidartinib) and supplemented the therapy with αPD-1 or IgG (control)." (PMID 35292516, 2022). "To assess the contribution of TAMs to INHBA-driven tumor growth, we treated YUMM3.3 tumor-bearing mice with anti-mouse colony stimulating factor 1 receptor (CSF1R) antibodies or isotype controls." (PMID 35580932, 2022). "Inflammatory monocyte mobilization decreases patient survival, and targeting the CCL2/CCR2 or CSF1/CSF1R axis that allows targeting macrophages or myeloid cell lineages improves chemotherapeutic efficacy and anti-tumour T-cell response." (PMID 36077801, 2022). "CSF-1/CSF-1R signaling is a key activator of the mononuclear phagocyte system, and blockade of CSF-1/CSF-1R creates an environment of reduced immunosuppression and enhanced interferon response that can impede tumor growth." (PMID 35874717, 2022). "At the same time, anti-CSF-1R can significantly reduce the ratio of MDSCs in tumor-infiltrating immune cells and resulted in greater inhibition of tumor angiogenesis and tumor growth when combined with anti-VEGFR-2 antibodies." (PMID 36225938, 2022). "Overall, results of the completed studies utilizing CSF-1R inhibitors suggest that combination of these biologically active drugs with anti-PD-1 therapy alone is insufficient to produce significant anti-tumor activity in advanced PDAC." (PMID 36077755, 2022). "CSF1 is a tumor‐promoting cytokine, with the participation of tumor cells, it binds to CSF1R of macrophages, attracts macrophages to the tumor area, and further accelerates the production of TAMs." (PMID 35593325, 2022). "This is a very aggressive tumor model that shows minimal response to anti–PD-1 therapy and is nonresponsive to other macrophage-depleting therapies such as anti-CSF1R." (PMID 35179953, 2022). "Zhu and colleagues found CSF1R expression in human PDAC tumor cells as well as intra-tumoral (TAM) macrophages, similar to what we see in PDAC CTC." (PMID 35316296, 2022). "Together, these results, along with our previous findings, articulate the potential role of GSNO as a combinatorial partner to augment the anti-tumor effects of CSF1R inhibition against CRPC." (PMID 36209194, 2022). "Multiple studies have demonstrated that CSF-1/CSF-1R is highly expressed in several tumor tissues such as breast cancer, prostate cancer, head and neck cancer, ovarian cancer, gastrointestinal cancer, colon cancer, pancreatic cancer, and mesothelioma." (PMID 36359228, 2022). "The same tracer dynamics were observed for tumor-based [18F]FET VOI under CSF-1R inhibition and withdrawal." (PMID 35804911, 2022). "Previous studies with this model show limited tumor growth inhibition to other macrophage-targeted therapies including anti-CSF1R antibodies." (PMID 35179953, 2022). "The infiltration of tumor-associated macrophages (TAMs) and increased expression of their associated genes, CD163 and CSF1R, were significantly observed in SHH MBs." (PMID 36358838, 2022). "M1 macrophage cytotoxicity against tumor cells was more efficient when CSF1R was inactivated in CAFs." (PMID 35315360, 2022).
tumor (continued). "Polarization of TAMs toward the M2 phenotype is driven by the CSF1 (mainly secreted by tumor cells)/CSF1 receptor (CSF1R) axis." (PMID 35315360, 2022). "Direct inhibition of this interaction between CSF-1 and CSF-1R, in combination with paclitaxel, was shown to inhibit TAMs and improve infiltration of T-cells into tumor islets." (PMID 35158750, 2022). "The reduction in the accumulation of the MDSCs expressing CSF-1R+CD11c+ seems to be mediated, at least in part, by a reduction in tumor-derived CSF-1." (PMID 35292516, 2022). "The CSF-1R plays an important role in the macrophage’s proliferation and differentiation, which can be stimulated by tumor cells via CSF1 secretion (CSF-1R ligand).." (PMID 35526184, 2022). "Some studies indicated that CSF-1R is mainly expressed in tumor cells, while CSF-1R has also been reportedly expressed in TAMs and critically involved in tumor immune escape." (PMID 35444953, 2022). "Q702 inhibited the phosphorylation of Axl, Mer, and CSF1R in tumor samples from human tumor xenograft models as well as in Axl, Mer, or CSF1R-overexpressing cell lines." (PMID 36230744, 2022). "Results showed that blocking CSF1R reversed Lal–/– CD11c+ cells’ suppressive activity on T cell proliferation and impaired stimulation of tumor growth in mice." (PMID 35917184, 2022). "IL-34 stimulates CSF1R in TAMs to promote their survival and in monocytes to promote their recruitment to the tumor area." (PMID 36359228, 2022). "One reason is that CSF1R inhibitors lead to accumulation of a large number of immunosuppressive cells in the tumor site." (PMID 35672862, 2022). "Overall, it is possible that aging leads to an increased potential for monocyte to macrophage differentiation, through CSF-1R signaling/increased CSF-1 utilization, that is mediated by both the aging and tumor microenvironment." (PMID 35821822, 2022). "We found that CSF-1R was significantly correlated with tumor-related immunosuppressive molecules including PDCD1, CTLA4, CD80, CD86, HAVCR2, etc.." (PMID 35444953, 2022). "Some studies have revealed that CSF1 produced by tumor cells can accelerate the accumulation of TAMs, and CSF1R signaling blockade can delay tumor progression and reduced metastasis by depleting TAMs." (PMID 35593325, 2022). "Blockade of CSF-1R reduced tumour cell proliferation and enhanced apoptosis in vivo, despite minimal cytotoxic effects on tumour cells in vitro, highlighting the importance of TME-derived GAMs in driving tumour cell progression." (PMID 33803414, 2021). "Of particular interest is colony stimulating factor 1 receptor (CSF1R, M-CSFR, c-FMS, CD115) and its role in regulating plasticity of tumor-associated macrophages." (PMID 33842370, 2021). "This phenomenon was observed after anti CSF-1R therapy, which causes increased infiltration of the tumor by PMN-MDSC (and it is stated as one of the reasons for failure of CSF-1R targeted monotherapy)." (PMID 33418996, 2021). "It was recently shown that depletion of TAM by an anti-CSF-1R enhanced the anti-tumor effect of docetaxel in a murine epithelial ovarian cancer." (PMID 33418996, 2021). "PET imaging in non-tumor-bearing mice revealed low blood pool levels of [89Zr]Zr-DFO-N-suc-CSF1R-mAb with SUVmean of 0.3 ± 0.04 at 24 h and 0.2 ± 0.04 at 72 h after injection." (PMID 34976826, 2021). "To further define mechanisms regulating CSF1R-targeted therapies, we systematically evaluated the effect of anti-CSF1R treatment on tumor growth and tumor microenvironment (TME) inflammation across multiple murine models." (PMID 33511454, 2021). "Colony stimulating factor (CSF), secreted by GBM cells, facilitates TAM recruitment and treatment with CSF-1 receptor (CSF-1R) antagonists has resulted in reduced infiltration of TAMs, decreases in tumor volume and increased survival of mice." (PMID 33668856, 2021).
tumor (continued). "Combining CSF1R blockade with anti-PD-1 or anti-CTLA-4 inhibitors showed improved tumor response compared with single-arm anti-PD-1 or anti-CTLA-4 treatment." (PMID 33922556, 2021). "IL-34 secreted by chemo-resistant tumor cells in a paracrine manner enhanced the polarization of M2 TAMs by activating colony stimulating factor 1 receptor (CSF1R)/AKT signaling pathway." (PMID 34095111, 2021). "Knowledge about CSF1R biology and its role in cancer is evolving rapidly, especially regarding the supportive tumor microenvironment." (PMID 33842370, 2021). "An inhibitor of the CSF1R was able to increase survival and decrease the tumor volume in a proneural GBM mouse model." (PMID 34434898, 2021). "As the presence of CSF1R+ cells in TME correlates with tumor progression, metastasis, and poor survival in various tumor types, targeting CSF1R signaling in TME cells is an appealing strategy." (PMID 33544755, 2021). "Inhibiting CSF-1R in a mouse model of glioblastoma can lead to obvious decrease in tumor volume and a significant increase in mouse survival." (PMID 33391402, 2021). "Meanwhile, remaining TAMs are reprogrammed by CSF1/CSF1R blockade to support antigen presentation and bolster T-cell activation, which further restrains tumor progression." (PMID 34201127, 2021). "Within the tumor, monocytes differentiate into immunosuppressive macrophages via the CSF1R pathway in response to M-CSF and potentially IL-34 secretion by tumor cells." (PMID 34178677, 2021). "For example, the deletion of PI3Kγ improved survival and responsiveness to standard-of-care chemotherapy in animal models of PDAC, and the dual inhibition of PI3Kγ and CSF-1/CSF-1R reduced the tumor infiltration of MDSCs and inhibited tumor growth." (PMID 34356110, 2021). "The emergence of a population resistant to the BRAF inhibitor was associated with an increase in CSF-1R and IL-34 expression, and activation of ERK1/2 and AKT signaling pathways to promote tumor survival and proliferation." (PMID 33408768, 2021). "We demonstrate here that STAT5 deletion using the Csf1r-iCre model led to enhanced tumor cell metastasis to the lung." (PMID 34743736, 2021). "In experimental mesotheliomas, CSF1R inhibition abrogates tumor progression by limiting suppressive myeloid populations and enhancing CD8+ cell activation and acts synergistically with anti-PDL1." (PMID 34067348, 2021). "This does not imply any significance in terms of direct changes in the macrophage population but it suggests that macrophages present in the tumor responded to treatment and altered their relationship with the tumor, because they express CSF1R." (PMID 34899694, 2021). "Combining olaparib treatment with macrophage-targeting therapy by CSF1R-blocking antibodies significantly enhances the antitumour immune response and increases survival in mice with BRCA-deficient TNBC tumours." (PMID 34885119, 2021). "Using genetic approaches, we demonstrate that STAT5 deletion via a Csf1r-driven Cre expression model enhances tumor cell metastasis to the lungs." (PMID 34743736, 2021). "A preclinical study demonstrated that the combination of a CSF-1R inhibitor with PD-1 or CTLA4 antagonists elicited tumor regression, while the single use of PD-1 or CTLA4 inhibitors showed limited efficacy." (PMID 33802565, 2021). "For example, the colony-stimulating factor-1 receptor (CSF-1R) is an attractive combination immunotherapeutic agent for tumor treatment by targeting TAMs." (PMID 34616742, 2021). "Tenosynovial giant cell tumors (TGCTs), for example, are a rare and locally aggressive type of tumor characterized by high levels of CSF-1 and overexpression of CSF-1R+ macrophages." (PMID 34178692, 2021). "Targeting the M-CSF/CSF1R axis can reduce tumour progression in multiple murine cancer models including PDAC29,43–45." (PMID 33627655, 2021). "Consistent with this, we found in tumor-bearing mice that anti-CSF1R diminished the number of necrotic lesions detected in the liver after chemoimmunotherapy." (PMID 34101617, 2021).